BDNF (brain derived neurotrophic factor)
Diseases named in the same sentence as BDNF in open-access papers (continued):
Sharing a sentence is not in itself a finding about the gene and the disease.
depression (continued). "In stress-induced animal models of depression, BDNF was shown to be markedly reduced by IL-1β and TNF-α and their downstream signaling pathways including NF-κB." (PMID 31019266, 2020). "For example, BDNF/TrkB signaling has opposite effects on depression and anxiety depending on the brain region investigated." (PMID 32087746, 2020). "Brain-derived neurotrophic factor (BDNF) is a neurotrophic factor that is pivotal in our understanding of the pathophysiology of depression." (PMID 33312794, 2020). "Preliminary evidence has demonstrated that patients with major depressive disorder (MDD) present a hypomethylation of the CpG-87 site of the promoter IV region of BDNF gene and are less likely to benefit from antidepressants." (PMID 33096634, 2020). "In those patients in the placebo or medical treatment only groups, a higher BDNF methylation at CpG-1 of exon VI and a higher percent methylation of exon VI predicted persistence of depression at the one year follow-up." (PMID 32012861, 2020). "By their nature NTs play a key role in preventing depressive disorders, and data obtained in rodent models of depression indicate that administration of BDNF and NGF have significant antidepressant effects." (PMID 33066277, 2020). "First, BDNF is involved in the origin of depression and in antidepressant effects and NTS enhanced BDNF." (PMID 32792925, 2020). "Emerging evidence has indicated the involvement of BDNF in depression, including PPD, on the basis of its roles in pathogenesis and treatment of depression." (PMID 32532322, 2020). "In conclusion, fRG and its constituents Rd and protopanaxatriol mitigated anxiety/depression and colitis by regulating NF-κB-mediated BDNF expression and gut dysbiosis." (PMID 32224881, 2020). "Our results indicate that the BDNF-FoxO1 axis in mPFC can regulate depression-related behaviors and stress vulnerability in postpartum female mice." (PMID 32532322, 2020). "The brain-derived neurotrophic factor (Bdnf) gene is an important target gene for the study of depression and antidepressant therapy." (PMID 32532322, 2020). "The expression of BDNF was negatively correlated with the severity of depression, and female patients had lower BDNF levels." (PMID 32351365, 2020). "The increase in fecal Enterobacteriaceae has been also reported in patients with major depressive disorders, accompanied by a low level of brain-derived neurotrophic factor (BDNF) in the blood." (PMID 32546239, 2020). "BDNF is involved in activity‐dependent neuronal plasticity, and evidence from clinical studies shows that decreased activity of BDNF occurs in the brain of patients with major depression." (PMID 31875662, 2020). "Butyrate maintains BDNF (brain-derived neurotrophic factor) levels and neurogenesis in the hippocampus and improves depression-like behavior." (PMID 32933067, 2020). "In a rat model of depression, the concentration of BDNF is reduced in the hippocampus, and the release of BDNF seems to mediate the rapid action of ketamine in PFC." (PMID 32188010, 2020). "The knockdown of TrkB produces anxiety-like behavior and the deletion of BDNF increases depression-like behavior." (PMID 32351365, 2020). "The role of n3 PUFA in the pathogenesis of depression can result from the effect on the intracellular transmission, pre- and postsynaptic transmission or brain-derived neurotrophic factor (BDNF) synthesis." (PMID 32717948, 2020). "Repeated administration of METH leads to a marked increase in BDNF–TrkB signaling in the nucleus accumbens shell, eventually resulting in the long-lasting depression-like behavior that was observed in mice after METH withdrawal." (PMID 32210759, 2020). "PbA-infected mice presented increased parasitemia, adherent leukocytes, blood-brain barrier permeability, and reduced BDNF protein levels, as well as depression-like behavior." (PMID 32843073, 2020).
depression (continued). "Several other studies found that aqueous extracts of saffron showed antidepressant effects in various experimental depression models that involved modulation of the BDNF, CREB, and VGF pathways." (PMID 33117172, 2020). "In summary, acupuncture-promoted plasticity protein BDNF expression seems to play an important role in the development of depression." (PMID 33029119, 2020). "Baseline BDNF levels are decreased in patients with MDD compared to healthy controls and the magnitude of a decrease in BDNF is negatively correlated with depression severity, as confirmed by meta-analyses." (PMID 33255237, 2020). "Another SSRI with affinity for Sigma1R citalopram altered DNA methylation of the promoters of genes associated with depressive disorders, including TSPO and BDNF in vitro." (PMID 32992988, 2020). "It is unclear to what extent co-morbid conditions, such as depressive disorder affect the relationship between BDNF and AUD." (PMID 32372985, 2020). "These patients had a recurrent severe (major) depressive disorder, which likely exhausted BDNF resources." (PMID 32883977, 2020). "These meta-analyses highlight the crucial role of BDNF in depressive disorders and specifically the impact of p.Val66Met SNP on geriatric depression." (PMID 33584494, 2020). "Among the neurotrophic factors involved in depressive disorders, brain-derived neurotrophic factor (BDNF) has gained much attention." (PMID 32331397, 2020). "BDNF plays important an role in neural development and the regulation of synaptic plasticity, which is diminished in depressive disorders." (PMID 33088274, 2020). "The role of BDNF in both pathophysiology and therapy of depressive disorders seems to be strongly confirmed." (PMID 32970734, 2020). "This epistasis interaction suggested that risk, as measured by psychiatric symptoms, particularly depression and anxiety, varied systematically depending on both 5-HTTLPR and BDNF alleles." (PMID 31440532, 2019). "Few studies using double-blind placebo-controlled design have investigated BDNF in major depression, and studies with psychedelic substances evaluating depression patients are scarce." (PMID 31231276, 2019). "In one study, supplementation with L. helveticus NS8 reduced restraint-stress induced behavioral and pathophysiological markers of depression, specifically including elevated levels of hippocampal BDNF." (PMID 31749681, 2019). "A reduction in BDNF protein levels has been suggested to promote the development of depression and its treatment resistance." (PMID 31350592, 2019). "Effects of PNS and depression on offspring neurogenesis and physiological outcomes, is limited and our findings showed dysregulation in signaling pathways and BDNF profile." (PMID 30718708, 2019). "Administrating tDCS over the cortex increases the level of BDNF and decreases the psychological symptoms such as depression, anxiety, stress, and craving for drugs." (PMID 32477481, 2019). "Animal models of depression suggest the vital function of BDNF in the pathophysiological mechanism of depression." (PMID 31231295, 2019). "In this report, we present the first detailed analysis of BDNF levels and depression in young Chinese acne vulgaris patients." (PMID 31234814, 2019). "BDNF has been studied as possible peripheral biomarkers of mood disorders, and the tPA–BDNF pathway in serum is a target for the treatment of depression." (PMID 31110484, 2019). "Despite this, studies with humans that analyze pro-BDNF/m-BDNF ratio in blood are infrequent, and few studies showed changed ratio in patients with major depression." (PMID 31231276, 2019). "In our study, we explored the role of BDNF, Wnt/β-catenin and Shh signalling in depression and the involvement of these signalling pathways in providing an antidepressant effect by nicotine." (PMID 31193084, 2019).
depression (continued). "The most recent meta-analysis has revealed significant increases of peripheral BDNF levels following antidepressant treatment in patients diagnosed with major depression." (PMID 31098654, 2019). "Chronic administration of CORT induced mice depression, which was associated with the downregulated expression of the molecular biomarkers of depression, such as BDNF and GR." (PMID 31888678, 2019). "In this section, we will further discuss the role of BDNF in the main psychiatric disorders: major depressive disorder, bipolar disorder, and schizophrenia." (PMID 30117106, 2019). "This SNP, known as the val66met, changes the 5-prime pro-domain of the human BDNF protein reducing BDNF protein secretion in the brain, and leading to increased vulnerability to depression." (PMID 31440532, 2019). "The ex-vivo study was aimed to investigate the potential effects of NIC on neurodevelopmental pathways such as BDNF, Wnt/β-catenin and Shh signalling pathways in CUMS induced depression and its associated cognitive deficits in rat brain." (PMID 31193084, 2019). "Significantly lower levels of serum BDNF were found in antidepressant-free patients with major depressive disorder compared with healthy controls, which findings were confirmed by a large cohort study and by three meta-analyses as well." (PMID 30767081, 2019). "A recent meta-analysis showed the relationship between stressful life events and depression was significantly moderated by BDNF levels." (PMID 31572245, 2019). "The elevated levels of ROS are capable of decreasing the expression of brain-derived neurotrophic factor (BDNF), partially contributing to the progress of depression." (PMID 31396300, 2019). "In particular, Molendijk and colleagues suggested that low serum BDNF levels are evident during depression and normalize during remission." (PMID 31118969, 2019). "A similar influence on BDNF has been observed in a case study of chronic bilateral DBS of the lateral habenula for treatment‐resistant depression: BDNF levels correlated in a reverse U‐shape with levels of depression scores." (PMID 30862663, 2019). "This is the first double-blind randomized placebo-controlled clinical trial that explored the modulation of BDNF in response to a psychedelic in patients with depression." (PMID 31231276, 2019). "The same study also demonstrated that treatment with SSRI citalopram alleviated depression and increased hippocampal BDNF expression and 5-HT levels." (PMID 32009871, 2019). "BDNF is also one of the most important targets of depression treatment, as chronic administration of antidepressant drugs increases BDNF expression level, which is followed by the proliferation and differentiation of neuronal progenitor cells." (PMID 30407505, 2019). "BDNF binds to the tropomyosin receptor kinase B (TrkB) whose downstream signaling pathways play an important role in the structural plasticity induced by depression." (PMID 31749681, 2019). "In the animal models of depression, the epigenetic modifications of the BDNF promoters have been investigated, particularly on BDNF exons I, IV, and IX." (PMID 31027379, 2019). "Zhile alleviated depression-like behaviors by upregulating the cAMP-CREB-BDNF (brain-derived neurotrophic factor) axis to exert neuroprotective effects." (PMID 30625977, 2019). "In contrast, BDNF levels are lower in schizophrenia, bipolar and depression, also using meta-analyses in each case." (PMID 31548888, 2019). "This study assesses the association between pre-treatment BDNF levels and ECT outcome in severe late-life unipolar depression (LLD)." (PMID 31127089, 2019). "Reductions in the BDNF level in the PFC induced by HFD and diabetes are implicated in the production of depression, which is achieved by activation of CREB." (PMID 32082151, 2019). "Elevated serotonin and BDNF level by catalpol significantly protect against depression and neurodegeneration." (PMID 31878316, 2019).
depression (continued). "Treatment of C. butyricum increased central 5-HT levels and BDNF expression in mice with reduced depression." (PMID 32009871, 2019). "In a chronic unpredictable stress model of depression, depressive symptoms were correlated to reduced BDNF levels in the hippocampus resulting in the mounting decrease in hippocampal CA1 pyramidal neurons." (PMID 31749681, 2019). "Brain-derived neurotrophic factor (BDNF) is a protein that has received considerable attention in the field of depression." (PMID 31127089, 2019). "Brain-derived neurotrophic factor (BDNF) is one of the proteins that contributes to the survival, growth, maintenance of neurons, and plays important roles in the pathophysiology of depression." (PMID 31234814, 2019). "Chronic stress can trigger both anxiety- and depression-like behaviors as well as reduce BDNF levels and additionally, cytokines can attenuate the BDNF level in depression." (PMID 31275120, 2019). "Our findings indicate a significant decrease of BDNF in the acne vulgaris patients with depression in compare with control subjects." (PMID 31234814, 2019). "Reduced BDNF levels have been reported in some psychiatric disorders and neurodegenerative diseases such as depression and Alzheimer’s disease, strongly indicating that BDNF inducers have beneficial effects in these diseases." (PMID 31413298, 2019). "In human patients, the reduced levels of BDNF in response to proinflammatory cytokines, psychological stress and cortisol stimulation have been reported to contribute to the development of depression." (PMID 31251738, 2019). "In particular, changes in DNA methylation at BDNF promoters I and IV have been detected in Alzheimer’s disease (AD), major depression, and schizophrenia, but such changes have not yet been explored in HD." (PMID 32038165, 2019). "It has been widely recognized that BDNF-TrkB signaling plays a pivotal role in the pathogenesis and therapeutic mechanisms of depression." (PMID 32116688, 2019). "The subjects were evaluated before and after tDCS by their serum level of BDNF, desires for drug questionnaire, and depression anxiety stress scale." (PMID 32477481, 2019). "Only the interaction of 5HTTLPR and BDNF accounted (Beta = −0.688, t = −3.52, p = .001) for a significant portion of the variance in depression." (PMID 31440532, 2019). "Our investigations showed that chronic unpredictable mild stress induced depression results declined expression of BDNF, Wnt/β-catenin, Shh and its downstream transcription factors GLI1/2/3 and NKX2.2 in the hippocampus of male Wistar rat." (PMID 31193084, 2019). "After delivery, the ablation of estrogen is observed to reduce the hippocampal BDNF levels, which acts to impair hippocampal neurogenesis and initiates depression- and anxiety-like behaviors in mice." (PMID 31406011, 2019). "Similar to its role in depression, central chronic neuroinflammation further activates afferent autonomic nerve pathways, decreases hippocampal 5-HT levels, decreases BDNF and contributes to persistent chronic pain." (PMID 31616368, 2019). "As 5-HT promotes BDNF synthesis, this presumably explains the concomitant increase in BDNF levels in PFC of rats ameliorated of depression with B. infantis treatment." (PMID 32009871, 2019). "Various preclinical and clinical investigations suggest a correlation between downregulation of hippocampal BDNF and pathogenesis of depression." (PMID 31139084, 2019). "Here we investigated serum BDNF levels in healthy controls (N = 45) and patients with treatment-resistant depression (N = 28) before (baseline) and 48 h after (D2) a single dose of ayahuasca or placebo." (PMID 31231276, 2019). "The reserpine-induced rat depression model significantly expressed higher levels of NF-κB, BDNF, and TrkB in the hippocampus of rats compared with the control group (P < 0.01)." (PMID 32009949, 2019).
depression (continued). "In geriatric women, a greater BDNF DNA methylation was observed in those with anxiety/depression compared to healthy controls, and interestingly, the difference was more pronounced in patients with the rs6265 CT genotype than with the CC genotype." (PMID 31027379, 2019). "al found that electroacupuncture at ST36 can regulate the expression of βCaMKII in the lateral habenular nucleus and the protein of hippocampal brain derived neurotrophic factor (BDNF) to relieve depression." (PMID 30854008, 2019). "In animal experiments, chronic stress and depression conditions decreased BDNF expression, increased apoptosis and decreased regeneration of neurons in the hippocampus, and also decreased BDNF expression in other parts of the brain." (PMID 31231295, 2019). "It is suggested that decreased expression of BDNF are related to depression, and which will become enhanced after antidepressant treatment." (PMID 31049031, 2019). "Recently studies tried to analysis the BDNF function in depression mechanism, by considering the important effect of BDNF in promoting the survival and differentiation of neurons, as well as enhancing dendritic spines complexity and synapses plasticity." (PMID 31234814, 2019). "Peripheral, subcutaneous BDNF injection evokes antidepressant-like effects in rodents, prevents depression-induced behavior due to chronic stress, and increases cell survival in both the hippocampus and PFC." (PMID 31572200, 2019). "During development, ryanodine-sensitive calcium release and BDNF-mediated synaptic depression can produce selective stabilization of inputs with similar spontaneous activity over distances of 5–10 μm." (PMID 31663507, 2019). "Since BDNF has emerged as a possible biomarker for depression, we compared BDNF concentration in the hippocampus of Ghsr-/- mice and Ghsr+/+ littermates, at baseline state and after CSDS exposure." (PMID 31057357, 2019). "Previous studies showed that patients with depression, as well as various animal models of depression, had reduced BDNF levels in the hippocampus." (PMID 31847138, 2019). "A recent review examining the 5-HT1A receptor in depression suggested interaction between BDNF and HTR1A as an important target for future PET studies." (PMID 30664620, 2019). "The next step of our study examined cerebral tPA and BDNF levels in several brain structures related to depression (prefrontal cortex, hippocampus, hypothalamus) in PAI-1−/− and PAI-1+/+ mice." (PMID 31610810, 2019). "Collectively, our research indicates that Rb1 exerts antidepressant-like effects in a mouse model of CUMS-induced depression by promoting BDNF signaling, thus providing new insights into the pharmacological effects of Rb1 in the treatment of depression." (PMID 31572200, 2019). "In depression, GSK3β abnormal activation suppresses BDNF expression, which regulates neural proliferation, neurogenesis, synaptic plasticity, and apoptosis." (PMID 30407505, 2019). "In general, lower serum levels of BDNF are correlated with depression severity in patients with acne vulgaris." (PMID 31234814, 2019). "A significant negative correlation was seen between the change from baseline to week 26 for plasma BDNF levels and changes from baseline to week 26 regarding the score of the Calgary Depression Scale for Schizophrenia (CDSS)." (PMID 31098654, 2019). "For instance, previous reports have found a relationship between VO2max, inflammation, and brain-derived neurotrophic factor (BDNF) in different populations, factors also recognized to be related to depression." (PMID 31031652, 2019). "The present results showed that a decrease in the BDNF level in the PFC was observed, and pretreatment with AST reversed the reduction of BDNF in this diabetes co-morbidity with depression model." (PMID 32082151, 2019). "Strong stressful situations can trigger a state of vulnerability to depression in some individuals, which can be identified with low serum BDNF levels." (PMID 31331937, 2019).